TAT (tyrosine aminotransferase)
Diseases named in the same sentence as TAT in open-access papers:
TAT is named in the same sentence as 54 diseases in open-access papers, as found by Europe PMC text mining. Sharing a sentence is not in itself a finding about the gene and the disease. The quoted sentences say what the papers report.
tyrosinemia (9 papers, 2018 to 2025). An autosomal recessive inherited metabolic disorder caused by mutations in the FAH, HPD, and TAT genes. "For example, TAT is primarily expressed in the liver, but a deficiency in TAT leads to tyrosinemia, which has systemic and ocular effects due to the accumulation of tyrosine and its byproducts." (PMID 40548636, 2025). "Tyrosinemia type II, or oculocutaneous tyrosinemia, results from a deficiency of hepatic tyrosine aminotransferase." (PMID 39050308, 2024). "Tyrosinemia type II (OMIM 276600) or oculocutaneous tyrosinemia occurs secondary to a deficiency of the cytoplasmic enzyme, tyrosine aminotransferase (TAT: EC 2.6.1.5)." (PMID 36471409, 2022). "The increase of phenylpyruvic acid content in urine reflects the abnormal metabolism of phenylalanine, suggesting that intracellular tyrosine aminotransferase causes hepatocyte injury and tyrosinemia." (PMID 35153793, 2022). "The activity of the catabolic enzyme tyrosine aminotransferase (TAT) varies across species including humans and it is hypothesized that this primarily accounts for the different levels of tyrosinemia observed between species and leads to the subsequent differences in toxicity." (PMID 36800004, 2023). "Tyrosinemia is featured by elevated tyrosine and its derivatives in serum and urine due to defected enzymes in tyrosine-catabolic pathway, such as FAH, TAT, and HPD20." (PMID 31537781, 2019).
hepatocellular carcinoma (5 papers, 2013 to 2025). A malignant tumor that arises from hepatocytes. "Among the top expressed genes was TAT, which encodes the mitochondrial enzyme tyrosine aminotransferase, involved in tyrosine metabolism and recognized as a novel tumor suppressor gene linked to hepatocellular carcinoma (HCC)." (PMID 40225267, 2025). "The in vitro gluconeogenic potential of GRM-01 was examined in cultures of the human hepatoma cell line, HepG2, where the induction of TAT enzyme activity was determined." (PMID 40110125, 2025). "Abnormal expression of the tyrosine catabolic enzyme tyrosine aminotransferase (TAT) has been reported in patients with hepatocellular carcinoma (HCC)." (PMID 32542016, 2020). "Tyrosine aminotransferase has also been found to be a tumor suppressor gene in human hepatocellular carcinoma (HCC)." (PMID 24385923, 2013). "Additionally, the enzyme tyrosine aminotransferase (TAT), which acts to normally convert tyrosine to energy, has been identified as a tumor suppressor gene which acts to promote apoptosis and prevent the development of hepatocellular carcinoma." (PMID 24385923, 2013). "In HepG2 hepatocellular carcinoma cells, BoA down-regulated the corticosteroid-binding globulin (CBG) gene expression, a marker for GR transrepression, without up-regulating tyrosine aminotransferase (TAT) gene expression, a marker of GRE transactivation." (PMID 36012159, 2022).
Tyrosinemia type 2 (5 papers, 2020 to 2024). "To date, 33 mutations in TAT from 42 families (74 patients) have been described to cause tyrosinemia type II." (PMID 36471409, 2022). "Tyrosine aggregations have been described in the cornea and skin of patients with tyrosinemia type II, a congenital metabolic disease caused by deficiency of the enzyme tyrosine aminotransferase." (PMID 34417872, 2021). "Tyrosinemia type II and III are autosomal recessive disorders caused by pathogenic variants in the tyrosine aminotransferase (TAT), and 4-hydroxyphenyl-pyruvate dioxygenas (HPPD) genes, respectively." (PMID 36471409, 2022). "Tyrosinemia type II, also known as Richner-Hanhart Syndrome (OMIM # 276600), is a rare autosomal recessive disorder, caused by mutations in the gene encoding tyrosine aminotransferase and is manifested by eye, skin, and central nervous system alterations." (PMID 33319750, 2020). "A defect in tyrosine aminotransferase, the first enzyme of the tyrosine degradation pathway, leads to hereditary tyrosinemia type 2 (HT2), also known as the Richner-Hanhart syndrome." (PMID 36702867, 2023).
glioma (4 papers, 2019 to 2023). A benign or malignant brain and spinal cord tumor that arises from glial cells (astrocytes, oligodendrocytes, ependymal cells). "Thrombin‐antithrombin (TAT) complex in plasma from glioma patients and healthy subjects were measured by ELISA." (PMID 34288521, 2021). "To confirm the effect of the TAT-TROY (234–371 aa) protein on endogeneous TROY/RKIP interaction, we tested whether the TAT protein could be transported into the glioma cells." (PMID 30337686, 2019). "On the other hand, tyrosine aminotransferase (TAT), HPD, HGD, and FAH were identified as unfavorable prognostic factors in glioma patients in the validation set." (PMID 37786553, 2023). "Gene expression in glioma is known to be spatially distinct, for example, presenting differential upregulation of tyrosine aminotransferase—where increased expression in the tumor core as opposed to the periphery was reported—and a corresponding activation of the tyrosine metabolism." (PMID 37652542, 2023).
breast carcinoma (3 papers, 2019 to 2026). "As an example, in the selected breast cancer sample, top-scoring SVGs follow distinct patterns, exemplified by the genes decorin (DCN) and tyrosine aminotransferase (TAT)." (PMID 41160880, 2026). "A statistically significant increase was noted for NET nucleosomes, thrombin–antithrombin complex (TAT), thrombomodulin (TM), and CRP in breast cancer patients with reduced LVEF > 10% (p < 0.05) compared to the patients with normal LVEF in response to DOX-based chemotherapy." (PMID 37444400, 2023). "Surprisingly, the most significant gene, TAT (Tyrosine aminotransferase), has not been reported to have a role in breast cancer." (PMID 31703592, 2019). "Among them, only Tyrosine aminotransferase (TAT) which is the first rank genes is not reported as a significant gene in cancer and we showed that this gene is frequently down regulated in tumor samples of breast cancer." (PMID 31703592, 2019).
influenza infection (3 papers, 2017 to 2022). "In present study, the recombinant protein TAT-NP, a fusion of TAT and NP was effectively expressed in Escherichia coli and purified as a candidate component for an influenza vaccine." (PMID 32811334, 2020).
Insulin resistance (3 papers, 2017 to 2022). Increased resistance towards insulin, that is, diminished effectiveness of insulin in reducing blood glucose levels. "Hyperinsulinemia as a result of insulin resistance in diabetes can activate the tyrosine aminotransferase." (PMID 35741945, 2022). "Insulin increases the activity of tyrosine aminotransferase, an enzyme that catalyzes tyrosine transamination and while in insulin resistance, circulating insulin may maintain adequate glucose metabolism, tyrosine breakdown may be affected." (PMID 34823524, 2021). "However, repression of tyrosine aminotransferase during states of insulin resistance and DM may result in the increased levels of circulating Tyr and Phe as observed in our study." (PMID 29165132, 2017).
diabetes (2 papers, 2022). "Thus, we next measured expression of Pgc-1α and a GR target gene tyrosine aminotransferase (Tat) to analyze activation status of these regulatory pathways in response to the STZ-induced diabetes and the potential effect of insulin therapy." (PMID 35524739, 2022).
endotoxemia (2 papers, 2013 to 2021). "Thrombin–antithrombin (TAT) complexes and plasminogen activator inhibitor type-1 (PAI-1) increased in circulation during endotoxemia." (PMID 34093202, 2021). "Treatment with 4 mg/kg 8-ol markedly reduced the secretion of TAT and PAI-1 in the plasma of WT mice, which indicated that 8-ol could prevent caspase-11–dependent DIC in endotoxemia." (PMID 34093202, 2021).
hypercoagulability (2 papers, 2020 to 2021). "We aimed to determine if the presence of CTCs and plasma markers of hypercoagulability [thrombin–antithrombin III (TAT), fibrinogen and d-dimer] are biomarkers of survival in MBC." (PMID 31473984, 2020). "We aimed to determine if the combination of CTC enumeration and quantification of systemic hypercoagulability [thrombin–antithrombin III (TAT), fibrinogen and d-dimer] is a biomarker of reduced overall survival in MBC." (PMID 31473984, 2020). "Overall, patients with stable COPD exhibit major alterations of fibrinogen, FII, FV, FVII, FVIII, FIX, D-dimers, von Willebrand factor Ag, von Willebrand factor Ac, TF, TAT, FPA, β-thromboglobulin, tPA-PAI, prothrombin fragment 1 and 2, and maximum thrombin levels, pointing to hypercoagulability." (PMID 34441381, 2021).
Hyperglycemia (2 papers, 2010 to 2020). An increased concentration of glucose in the blood. "It exhibited a better safety profile with regard to growth inhibition and induction of skin atrophy after long-term topical application, thymocyte apoptosis, hyperglycemia, and hepatic tyrosine aminotransferase activity." (PMID 20824100, 2010). "Mapracorat exhibits a better safety profile with regard to growth inhibition and induction of skin atrophy after long-term topical application, thymocyte apoptosis, hyperglycaemia, and hepatic tyrosine aminotransferase activity in animal models." (PMID 20824100, 2010). "The resulting GRE-driven upregulation of tyrosine aminotransferase (TAT), glucose 6-phosphatase (G6P) and phosphoenolpyruvate carboxykinase (PEPCK) for instance leads to hyperglycemia." (PMID 33071974, 2020).
liver cancer (2 papers, 2013 to 2017). An epithelial or non-epithelial malignant neoplasm that arises from the liver. "The enzyme tyrosine aminotransferase, which removes tyrosine from the body, has also been identified as a tumor suppressor gene, and this enzyme normally acts to prevent the development of liver cancer." (PMID 24385923, 2013). "Genes specifically expressed in liver cells [i.e., albumin (ALB) and tyrosine aminotransferase (TAT)] and a gene expressed in liver cancer/immature cells [i.e., α-fetoprotein (AFP)] were used as endogenous control genes." (PMID 29065189, 2017). "Consistent with an inhibitory role in the pathogenesis of liver cancer, transfection of HCC cancer cell lines with a tyrosine aminotransferase transgene suppressed malignant behavior such as growth in soft agar and the formation of tumors in nude mice." (PMID 24385923, 2013).
malaria (2 papers, 2009 to 2014). Malaria is a serious and sometimes fatal disease caused by a parasite that commonly infects a certain type of mosquito which feeds on humans. "An NCBI search for “tyrosine aminotransferase and malaria” identifies a paper that implicates this enzyme in malaria pathophysiology (yielding a DiCE Score of 4 for tyrosine aminotransferase)." (PMID 25071867, 2014). "Low antigen levels are likely to be due to increased consumption from thrombin binding in thrombin–antithrombin (TAT) complexes as TAT complexes are significantly increase in severe malaria; suggesting AT III is ‘mopping up’ excess thrombin." (PMID 19450727, 2009).
Chorioretinal atrophy (1 paper, 2020). Atrophy (wasting) of the choroid and retinal layers of the fundus. "Other ophthalmological features that are seen in glutamate related disorders are optic atrophy in some GLS loss patients; herpetiform corneal ulcerations in patients with TAT deficiency; chorioretinal atrophy in OAT deficient patients; and retinal degeneration in BCAT2 deficient patients." (PMID 31603991, 2020).
coinfection (1 paper, 2018). The simultaneous infection of a host by multiple pathogen species. "The pathogenesis of HIV/HHV-8 coinfection is complex and can be influenced by viral factors; for example, HIV induces the HHV-8 lytic cycle through the activation of the RTA protein and the TAT protein, and HHV-8 interferes with HIV replication by regulating the LTR by LANA antigen." (PMID 30482213, 2018).
dengue (1 paper, 2020). "We therefore support the use of blood coagulation biomarkers (such as coagulation times, Fibrinogen, TAT complex, vWF, and DD), often not considered, to define severity end points in future dengue studies." (PMID 32544159, 2020).
depression (1 paper, 2025). "In depression, diminished dopamine signaling disrupts the regulatory control over tyrosine aminotransferase (TAT) by impairing D1 receptor-mediated cAMP activity." (PMID 40137144, 2025).
gallbladder cancer (1 paper, 2025). "For instance, tyrosine aminotransferase (TAT) is a key regulator for liver metastasis of gallbladder cancer by potentiating cardiolipin-dependent mitophagy." (PMID 40735642, 2025).
glioblastoma (1 paper, 2011). The most malignant astrocytic tumor (WHO grade IV). "The TAT-Pyk2-AP fusion protein (150 nM) significantly reduced the pro-apoptotic effect of downregulation of FIP200 in both the U-87MG glioblastoma cells and the primary human brain MvEC." (PMID 21602932, 2011).
hemorrhagic stroke (1 paper, 2023). A stroke caused by a bleed on the brain. "Meta‐analysis of clinical studies showed that both ischemic (IS) and hemorrhagic stroke patients had higher thrombin‐antithrombin complex (TAT) levels and lower antithrombin (AT) levels which were persistent in the acute and subacute phase of IS." (PMID 37017398, 2023).
homocysteinemia (1 paper, 2022). "There was only one positive case for tetrahydrobiopterin deficiency (BH4D), homocysteinemia (HCY), ornithine transcarbamylase deficiency (OTCD), and tyrosine aminotransferase type II deficiency (TYR II- deficiency)." (PMID 36246604, 2022).
lymphoma (1 paper, 2008). A malignant (clonal) proliferation of B- lymphocytes or T- lymphocytes which involves the lymph nodes, bone marrow and/or extranodal sites. "Another example that induced apoptosis in melanoma, lymphoma and pancreatic carcinoma cells is a Bim-related BH3 domain linked to the HIV TAT protein for better membrane transduction (TAT-Bim)." (PMID 19506730, 2008).
murine typhus (1 paper, 2012). "Coagulation activation, with high plasma concentrations of TAT complexes and sTF, was more pronounced in patients with scrub typhus than in patients with murine typhus (p <0.001)." (PMID 22192733, 2012).
Retinal hemorrhage (1 paper, 2015). Bleeding located within the retina. "On univariate analysis, none of the fibrin markers (fibrin monomers, FDPs, or d‐dimers), coagulation measurements (PT, TAT, antithrombin III, protein C, and fibrinogen), platelet count or DIC score was significantly associated with retinal hemorrhages (P > 0.1)." (PMID 26186686, 2015).
tyrosinemia type I (1 paper, 2019). "Dysfunction of metabolic enzymes, fumarylacetoacetate hydrolase (FAH), tyrosine aminotransferase (TAT), and 4-hydroxyphenylpyruvic acid dioxygenase (HPD) in the phenylalanine and tyrosine catabolic pathway results in tyrosinemia type I, II, and III, respectively." (PMID 31537781, 2019).
viral infection (1 paper, 2021). "Furthermore, in HIV viral infection, an additional oxidative stress can derive form the production and release of the TAT protein, as demonstrated by the very low GSH levels found in TAT-transgenic mice." (PMID 33808471, 2021).
tumor (17 papers, 2011 to 2025). "CD8+ T cells and Tregs were more frequent whereas follicular helper T cells were less frequent in TaT than in tumor tissues." (PMID 29670256, 2018). "In these cells, tyrosine aminotransferase expression also acted to inhibit tumor formation via the stimulation of apoptosis, but the exact molecular events are still unclear." (PMID 24385923, 2013). "Subclusters 2 and 8 exhibited high expression of the metabolic factors CYP3A4, OTC, PCK1 and TAT, suggesting that these genes may be involved in tumor cell metabolic reprogramming events." (PMID 38927691, 2024). "Higher levels of fibrinogen, TAT, and D-dimer, and greater proportion of patients with multiple scattered infarctions were observed in the poor prognosis group, which indicated a different mechanism of tumor-related AIS from the common atherosclerotic infarction." (PMID 34899584, 2021).
cancer (7 papers, 2015 to 2024). A tumor composed of atypical neoplastic, often pleomorphic cells that invade other tissues. "Elevated TAT indicates coagulation activation, which exists in cancer patients." (PMID 38304067, 2024). "Translating Ca-TAT/siRNA complexes as an anti-cancer strategy in the clinic is highly feasible." (PMID 27283985, 2016). "The enzyme tyrosine aminotransferase, which catalyses the first step in tyrosine catabolism and which an orthologue is lacking in P. marneffei, has been shown to promote apoptosis and prevent cell proliferation during cancer development in humans." (PMID 25812137, 2015). "Although the mechanism by which BTApep-TAT inhibited cancer progression was not determined clearly because the function of BORIS was not thoroughly investigated, the specificity of the BTApep-TAT interaction with BORIS may suggest that the formation of PROTACs induced BORIS degradation." (PMID 35918747, 2022).
infection (4 papers, 2017 to 2023). The state of being infected such as from the introduction of a foreign agent such as serum, vaccine, antigenic substance or organism. "FVIIa : AT, a marker of the extrinsic pathway, FXIa:C1inh, a marker of the intrinsic pathway, and TAT, a marker of a prothrombotic state, significantly increased between 3 and 18-24 months after infection." (PMID 37868959, 2023). "This LTR promoter is activated by the viral TAT transcription factor, which must be transferred from the HIV-1-producing Jurkat cells to TZM-bl cells via infection or membrane fusion-mediated cell content mixing, as dissected in more detail below." (PMID 37459363, 2023). "We found several TAT genes; among them one DEG (c54071_g1) in tyrosine metabolism pathway was obviously up-regulated after pathogen infection." (PMID 31644543, 2019).
cardiovascular diseases (1 paper, 2020). "Increased concentrations of TAT complex demonstrate intensified generation of thrombin in cardiovascular diseases, and thus it is one of the most sensitive thrombosis biomarkers, but is not very specific." (PMID 32121363, 2020).
TAT also shares sentences with these, for which no sentence is quoted: Alzheimer disease (2 papers); prostate carcinoma (2); AIDS (1); aneurysm (1); brain diseases (1); coagulopathy (1); coronary atherosclerosis (1); COVID-19 (1); developmental delay (1); hemostatic disorder (1); HIVinfection (1); Hyperinsulinemia (1); Hypoglycemia (1); lipodystrophy (1); melanoma (1); metabolic disease (1); optic atrophy (1); pancreatic carcinoma (1); potassium (1); retinal degeneration (1); schizophrenia (1); scrub typhus (1); skin atrophy (1); ulcerations (1).